BRPF1 (bromodomain and PHD finger containing 1)
Diseases named in the same sentence as BRPF1 in open-access papers (continued):
Sharing a sentence is not in itself a finding about the gene and the disease.
acute myeloid leukemia (3 papers, 2020 to 2022). Acute myeloid leukemia (AML) is a group of neoplasms arising from precursor cells committed to the myeloid cell-line differentiation. "Shima H and his colleagues found that BRPF1 interacts with MOZ to activate the HOX pathway and promote the progression of acute myeloid leukemia." (PMID 36276071, 2022).
glioma (3 papers, 2021 to 2024). A benign or malignant brain and spinal cord tumor that arises from glial cells (astrocytes, oligodendrocytes, ependymal cells). "Moreover, more experiments should be performed to elucidate the underlying mechanism of BRPF1 in glioma progression and the potential of GSK6853 as a glioma target drug in vivo." (PMID 34926268, 2021). "BRPF1, as an inflammatory signature gene in glioma, regulates glioma cell proliferation and colony formation, thereby being described as a potential drug target of primary lower-grade gliomas." (PMID 36077605, 2022). "In our study, inhibition of BRPF1 function or interference of BRPF1 expression reduced the proliferation of glioma cells in vitro." (PMID 34926268, 2021). "To investigate the drug target potential of BRPF1 in glioma, we selected the BRPF1-specific inhibitor GSK6853 to treat U87-MG and U251 glioma cell lines and determined the IC50 value of GSK6853 by CCK-8 assay." (PMID 34926268, 2021). "To further clarify the effect of BRPF1 expression on glioma cell proliferation, we first interfered with BRPF1 expression using shRNA in the U87-MG and U251 cell lines." (PMID 34926268, 2021). "These experiments indicated that BRPF1 is involved in glioma cell proliferation and is a potential drug target for the treatment of gliomas." (PMID 34926268, 2021). "According to the Human Protein Atlas database, the protein level of BRPF1 was higher in low- and high-grade gliomas than in normal brain tissue, and the highest expression level of BRPF1 was found in high-grade gliomas." (PMID 34926268, 2021). "Inhibition of BRPF1 function or knockdown of BRPF1 expression attenuated glioma cell proliferation and colony formation." (PMID 34926268, 2021). "Finally, we analyzed the immune cell landscape and transcriptional characteristics between the high- and low-inflammatory signature groups and identified BRPF1, which is related to the proliferation of glioma cells, as a potential drug target." (PMID 34926268, 2021). "The CCK-8 assay showed that inhibition of BRPF1 function suppressed glioma cell proliferation." (PMID 34926268, 2021). "Inhibition of BRPF1 function attenuated glioma cell proliferation and colony formation, suggesting that BRPF1 may participate in regulating the proliferation of glioma cells." (PMID 34926268, 2021).
acute leukemia (2 papers, 2016 to 2020). A clonal (malignant) hematopoietic disorder with an acute onset, affecting the bone marrow and the peripheral blood. "BRPF1 is a core subunit of the MOZ HAT that plays an important role for normal developmental process and associated with acute leukemia." (PMID 32457794, 2020). "BRPF1 (bromodomain PHD finger 1) is a core subunit of the MOZ histone acetyltransferase (HAT) complex, critical for normal developmental programs and implicated in acute leukemias." (PMID 26626149, 2016). "In addition to BRPF1/2/3, the PZP module is found in a range of proteins that also form translocation chimeras in acute leukemias, including JADE1/2/3 and AF10/17." (PMID 26626149, 2016).
schizophrenia (2 papers, 2021 to 2022). A major psychotic disorder characterized by abnormalities in the perception or expression of reality. "In addition to BRPF1, we identified three other LoF-intolerant genes with multiple deleterious ultra-rare SNVs/indels in the schizophrenia cohort studied, and compared results to findings from previous studies of schizophrenia and other disorders." (PMID 33526774, 2021).
Anxiety (1 paper, 2019). Intense feelings of nervousness, tension, or panic often arise in response to interpersonal stresses. "Here, we found that Brpf1 HTs show impaired learning and memory and decreased levels of anxiety-related behavior." (PMID 31213987, 2019). "Together, these behavioral tests indicate that Brpf1 heterozygote mice have defects in learning and memory accompanied by decreased anxiety-related behaviors, indicating that Brpf1 functions in cognitive behaviors in a dosage-dependent manner in mice." (PMID 31213987, 2019). "Brpf1 HTs exhibited reduced anxiety and defective learning and memory." (PMID 31213987, 2019). "An in vitro study of Brpf1 haploinsufficiency also demonstrated decreased frequency and amplitude of miniature EPSCs that may subsequently contribute to abnormal behaviors, including decreased anxiety levels and defective learning and memory." (PMID 31213987, 2019).
bone-marrow failure (1 paper, 2022). "Similar to MOZ mutations, patients with BRPF1 mutations do not show hematological abnormalities, although loss of BRPF1 leads to acute bone-marrow failure in mice." (PMID 36712963, 2022).
coloboma (1 paper, 2021). An abnormality in which a part of a structure in one or both eyes is missing. "Our findings support a previous association of coloboma with BRPF1 mutations and reiterate the proposition that C/M are part of the phenotypic spectrum associated with IDDDFP." (PMID 33418956, 2021). "Here, we report a novel de novo BRPF1 frameshift variant associated with coloboma and previously unreported microphthalmia." (PMID 33418956, 2021). "Coloboma and microphthalmia in index patient 6[II:1] could result from PAX6 downregulation due to reduced levels of BRPF1 protein, as haploinsufficiency of PAX6 is associated with C/M." (PMID 33418956, 2021). "Although ocular abnormalities have been described for IDDDFP as additional features, the occurrence of coloboma has only recently been reported for a single case with a nonsense BRPF1 mutation." (PMID 33418956, 2021).
colon cancer (1 paper, 2021). "For example, the drug mesalazine, used to treat inflammatory bowel disease but with an apoptosis-inducing and chemopreventative effect in colon cancer; DTI-Voodoo predicts mesalazine to interact with five proteins with PHD-type zinc finger domain: BRPF1, TRIM33, BAZ1A, RSF1 and DPF2." (PMID 34320178, 2021).
colorectal cancer (1 paper, 2021). A primary or metastatic malignant neoplasm that affects the colon or rectum. "In fact, not just in the in-house samples, BRPF1 was also upregulated in HCC, colorectal cancer and kidney cancer from TCGA database." (PMID 34285329, 2021).
intellectual disability syndromes (1 paper, 2024). "Brpf1 mutations have been linked to intellectual disability syndromes, where important muscle defects, such as hypotonia, have been observed in patients." (PMID 39637238, 2024).
melanoma (1 paper, 2021). A malignant, usually aggressive tumor composed of atypical, neoplastic melanocytes. "KDM6B, BRD2, and BRD3 were moderately to weakly expressed in melanoma samples, whereas weak staining intensity was observed for BRPF1 and EHMT2 in melanoma samples as compared with normal skin tissue indicating that they are significantly expressed at low levels in melanoma samples." (PMID 34771678, 2021). "Our analysis of publicly available Talantov melanoma datasets revealed that only EZH2, BRD7/9, BRD2/3/4, BRPF1, EHMT2, and KDM6B were significantly overexpressed at the mRNA level in patient melanoma tissue samples as compared to the normal skin samples." (PMID 34771678, 2021).
microphthalmia (1 paper, 2021). Congenital or developmental anomaly in which the eyeballs are abnormally small. "Of the seven patients diagnosed with colobomatous microphthalmia, potentially disease-causing variants were identified in three index patients (43%) in three different genes (PUF60, BRPF1, and TGFB2)." (PMID 33418956, 2021).
prostate tumors (1 paper, 2023). "In prostate tumors, accumulated BRPF1 protein accelerated the cell growth, stem-like properties, and migration of cancer cells, further supporting the role of BRPF1 in cancer stemness." (PMID 36674511, 2023).
cancer (13 papers, 2016 to 2025). A tumor composed of atypical neoplastic, often pleomorphic cells that invade other tissues. "Through the examination of clinical data obtained from a pan-cancer study, we categorized patients into low and high BRPF1 expression groups, which revealed a significant association between elevated BRPF1 expression and reduced OS." (PMID 38346967, 2024). "About 236 BRPF1 variants have been found in 211 individuals out of a total of 10,240 cancer patients from TCGA datasets, equivalent to a prevalence rate of 2%." (PMID 36077605, 2022). "To date, 159 cancer-relevant mutations, including reading frame-shift and translational termination aberrations, have been identified in BRPF1, with 12 of them in the PZP domain." (PMID 26626149, 2016). "The impact of each cancer-derived somatic BRPF1 mutation should be verified experimentally." (PMID 36077605, 2022). "Lastly, our analysis of BRPF1 expression in pan-cancer and PCa databases demonstrated its significant association with various clinical attributes, including the upregulation observed in taxane-exposed PCa patients, suggesting BRPF1 as a potential biomarker for the progression of PCa." (PMID 38346967, 2024). "In addition to mutations, accumulating findings have indicated BRPF1’s role in cancer." (PMID 36077605, 2022). "Thus, BRPF1 is frequently mutated in different cancer types." (PMID 36077605, 2022). "BRPF1 is known to be indispensable for embryonic development; however, its involvement in cancer, with the exception of limited studies, remains poorly characterized." (PMID 38346967, 2024). "While it was surprising to find lower BRPF1 expression in PCa among the analyzed cancer types, the elevated expression of BRPF1 in cases of local recurrence and metastasis suggests a potential contribution of BRPF1 to disease progression." (PMID 38346967, 2024). "In fact, in glioma, BRPF1 regulates cancer cell proliferation and colony formation and was recognized as a potential therapeutic target for primary LGG." (PMID 36674511, 2023). "Together, these results will be crucial for full understanding of the roles of BRPF1 in transcriptional regulation and in the design of small-molecule inhibitors for cancer treatment." (PMID 38072045, 2023). "Further examination of the RNA-seq data revealed that BRPF1 is a master regulator on the expression of key oncogenes essential for cell cycle progression, cancer stemness, epigenetic regulation, and signal transduction." (PMID 34285329, 2021). "Our findings not only demonstrated the therapeutic value of BRPF1 inhibitor in HCC treatment but also highlighted the emerging concept of targeting bromodomain-containing proteins as a new strategy for cancer treatment." (PMID 34285329, 2021). "One of them is V771G of BRPF1, a subunit of the MOZ/MORF histone acetyltransferase complexes, which remodel chromatin, regulate gene expression and are implicated in cancer development." (PMID 34344882, 2021). "In fact, BRPF1 functions as a master regulator to expedite the expression of multiple key oncogenes involved in various cancer-promoting functions." (PMID 34285329, 2021). "As for BRPF2 and BRPF3, little is known about their engagement in cancer development and progression, leaving an open question of whether they exert similar activity as BRPF1 in maintaining cancer stem cell-like phenotype." (PMID 36674511, 2023). "We will also summarize how MOZ-BRPF1 is linked to development via controlling cell stemness and how mutations or changes in expression levels of MOZ/BRPF1 can lead to developmental disorders or cancer." (PMID 36712963, 2022). "Taken together, BRPF1 might influence cancer immune infiltration to regulate OSC development and progression." (PMID 36276071, 2022).
cancer (continued). "Furthermore, about 1016 cases with copy number variation (CNV) events of BRPF1 are found in 11,115 cancer patients, corresponding to a rate of 10%." (PMID 36077605, 2022). "In general, the pathological role of BRPF1 in cancer development remains largely elusive." (PMID 34285329, 2021). "BRPF1 was involved in cell cycle progression, senescence and cancer stemness." (PMID 34285329, 2021). "Our result suggested that BRPF1 is a potential target for cancer epigenetic therapy." (PMID 34285329, 2021). "After all, these expression data from TCGA database reinforced our initial observation in the RNA-seq analysis, suggesting that BRPF1 may be essential for cancer development." (PMID 34285329, 2021). "Yet, the pathological and functional role of BRPF1 in cancer, especially liver carcinogenesis, is still largely unknown." (PMID 34285329, 2021). "Thus, the potential role of BRPF1 needs to be addressed individually between different cancers." (PMID 36712963, 2022). "The functional role of BRPF1 in cancer development remains largely unknown." (PMID 34285329, 2021). "Inhibition and knockout studies with BRPF1 in HCC showed that its overexpression induces tumor migration and proliferation, acting like an oncogene in this specific cancer." (PMID 36712963, 2022). "Similarly, BRPF1 is upregulated in HCC and contributes to chromatin remodeling and cancer stem-like phenotypes." (PMID 41323392, 2025). "Therefore, identifying the non-histone interactome of BRPF1 is pivotal in deciphering its role in diverse cellular processes, including its misregulation in diseases like cancer." (PMID 38072045, 2023).
neurodevelopmental disorder (11 papers, 2019 to 2026). A behavioral and cognitive disorder with onset during the developmental period that involves impaired or aberrant development of intellectual, motor, or social functions. "Our study helps to summarize available knowledge and report the first case of a de novo frameshift pathogenic variant in BRPF1 in two siblings with this neurodevelopmental disorder." (PMID 37946714, 2023). "Recent studies have linked BRPF1 mutations to a neurodevelopmental disorder." (PMID 41221126, 2025). "Previous studies indicated a role for BRPF1 in bone maintenance, development of vertebrates, mouse embryo, forebrain and fetal hematopoietic stem cells, as well as in learning and memory and causing neurodevelopmental disorders in humans when mutated." (PMID 38346967, 2024). "The behavioral phenotypes of Brpf1 HTs recapitulate the deficits observed in individuals with BRPF1 mutations and may act as a useful animal model for better elucidating the mechanism underlying Brpf1-haploinsufficiency-related neurodevelopmental disorders." (PMID 31213987, 2019). "Among these, haploinsufficiency ofSETD5, BRPF1, CRBN, ATG7, SLC6A11, GRM7, and ARPC4has been linked to neurodevelopmental disorders and cognitiveimpairment." (PMID 40995453, 2025). "We demonstrate that FBRSL1 associates with the transcription factor Yin Yang 1 (YY1) and binds upstream of Bromodomain And PHD Finger containing 1 (BRPF1) and Lysine Acetyltransferase 6 A (KAT6A), two epigenetic regulators involved in embryonic development and linked to neurodevelopmental disorders." (PMID 40658195, 2025).
tumor (8 papers, 2020 to 2024). "Indeed, we observed a significant relationship between BRPF1 expression and PCa progression, as higher expression was associated with increased Gleason score and tumor stage, indicating its prognostic potential." (PMID 38346967, 2024). "Indeed, we found a significant association between BRPF1 expression levels and PCa progression, with higher expression levels being correlated with increasing Gleason score and tumor stage." (PMID 38346967, 2024). "Beyond clinical attributes (Gleason score, tumor stage, therapy outcome, recurrence), metastatic PCa databases further supported the significance of BRPF1 in taxane resistance, as evidenced by its upregulation in taxane-exposed PCa patients." (PMID 38346967, 2024). "Last of all, we observed that targeting BRPF1 or using MVA inhibitor (atorvastatin) are effective to suppress USP35high PRAD in vivo tumor growth." (PMID 36357379, 2022). "Experimentally, we showed that BRPF1 gene ablation reduced cell proliferation rate and orthotopic xenograft tumor growth in mice." (PMID 34285329, 2021). "Lung metastasis was also suppressed by BRPF1 knockout, as evidenced by the ex vivo bioluminescence imaging of the lungs from tumor-bearing mice." (PMID 34285329, 2021). "We found that BRPF1 knockout in MHCC97L cells significantly reduced subcutaneous tumor growth in nude mice." (PMID 34285329, 2021). "In HCC, bromodomain and PHD finger containing-1 (BRPF1) induce the activation of oncogenes by stimulating gene promoter H3K14 acetylation, and BRPF1-targeted inhibitor GSK5959 demonstrates a promising capacity to ameliorate tumor progression in murine models of HCC." (PMID 38921460, 2024). "BRPF1 could directly activate the MVA pathway that provides a novel role of BRPF1 in tumor lipid metabolism." (PMID 36357379, 2022). "The upregulation of BRPF1 expression in HCC tumor samples may be affected by different aetiological factors." (PMID 34285329, 2021). "We generated the C4-2b-derived tumor model and found that targeting BRPF1 could significantly suppress USP35high in vivo PRAD growth, as shown by tumor volumes and weight." (PMID 36357379, 2022). "To examine whether pharmacological inactivation of BRPF1 could suppress HCC growth in vivo, we treated tumor-bearing nude mice with GSK5959 (30 mg/kg/day via intraperitoneal injection) for 2 weeks." (PMID 34285329, 2021).
genetic disorder (1 paper, 2019). "The reported family contributes to the current knowledge regarding this unique and newly recognized genetic disorder, and further implicates the role of BRPF1 in human brain development." (PMID 31020800, 2019).
infection (1 paper, 2021). The state of being infected such as from the introduction of a foreign agent such as serum, vaccine, antigenic substance or organism. "To study the synaptic transmission of hippocampal neurons upon Brpf1 knockdown, we performed whole-cell patch clamp recordings on cultured hippocampal neurons at DIV 15 after scramble or shBrpf1 infection at DIV3." (PMID 34485298, 2021).
BRPF1 also shares sentences with these, for which no sentence is quoted: apraxia (2 papers); Blepharophimosis (2); Strabismus (2); Cognitive Deficits (1); epilepsy (1); genitopatellar syndrome (1); inflammatory bowel disease (1); kidney cancer (1); lymphoma (1); microcephaly (1); myeloid leukemia (1); Neurodevelopmental delay (1); pediatric cancers (1); speech disorder (1); stomach cancers (1); triple-negative breast carcinoma (1).